HHATL (hedgehog acyltransferase like)
Description:
Negatively regulates N-terminal palmitoylation of SHH by HHAT/SKN.
Synonyms: C3orf3; GUP1; KIAA1173; MG56; OACT3; MSTP002; MBOAT3
Tractability: Antibody: UniProt predicts a signal peptide or a membrane-spanning region.
Gene: Protein-coding gene on chromosome 3 (42,692,661 to 42,703,260, reverse strand). Ensembl gene ENSG00000010282.
Subcellular location: Endoplasmic reticulum membrane
Gene Ontology:
Molecular function: protein binding
Biological process: negative regulation of N-terminal protein palmitoylation; regulation of protein modification process
Cellular component: perinuclear region of cytoplasm; endoplasmic reticulum; endoplasmic reticulum membrane
Genetic constraint (gnomAD): Loss-of-function variants: 47 observed, 58.03 expected, observed/expected ratio (o/e) 0.81, 90% interval 0.64 to 1.03. The upper end of that interval is the gene's LOEUF score, 1.03, which puts it in group 4 of 6, group 1 being the genes least tolerant of losing a copy. Missense variants: 603 observed, 654.63 expected, observed/expected ratio (o/e) 0.92, 90% interval 0.86 to 0.99. Synonymous variants: 237 observed, 262 expected, observed/expected ratio (o/e) 0.9, 90% interval 0.81 to 1.01.
Homologues: Orthologues: chimpanzee HHATL (99% identical), pig HHATL (95% identical), rat Hhatl (91% identical), mouse Hhatl (91% identical), guinea pig HHATL (90% identical), tropical clawed frog hhatl (65% identical), zebrafish hhatla (64% identical), zebrafish hhatlb (56% identical). Paralogues in human: HHAT (26% identical).
Diseases named in the same sentence as HHATL in open-access papers:
HHATL is named in the same sentence as 8 diseases in open-access papers, as found by Europe PMC text mining. Sharing a sentence is not in itself a finding about the gene and the disease. The quoted sentences say what the papers report.
congenital nemaline myopathy (1 paper, 2020). A rare genetic muscle disorder defined by muscle weakness and the presence of fine, thread-like or rod-like structures called “nemaline bodies”, when muscle biopsies are viewed under the microscope. "Hedgehog acyltransferase like (HHATL) is needed for normal postnatal skeletal muscle maturation while mutation of KLHL40 is linked to Nemaline Myopathy 8 and Severe Congenital Nemaline Myopathy reflecting the role of KLHL40 in regulating skeletal muscle development." (PMID 33182325, 2020).
epilepsy (1 paper, 2020). A brain disorder characterized by episodes of abnormally increased neuronal discharge resulting in transient episodes of sensory or motor neurological dysfunction, or psychic dysfunction. "The only study of HHATL related to the nervous system reported changes in the levels of HHATL protein in myocardial tissue in a rat epilepsy model." (PMID 33182325, 2020).
type 2 diabetes (1 paper, 2018). "Nine genes not previously reported to be associated with type 2 diabetes were significantly dysregulated in our organ donor and PPP cohorts (ANKRD23/39, ASCL2, HHATL, NSG1, PCDH20, SCTR, CD44, FAM102B and FBXO32)." (PMID 29185012, 2018).
cancer (3 papers, 2018 to 2025). A tumor composed of atypical neoplastic, often pleomorphic cells that invade other tissues. "Advancement-stage cancers (Group III) showed a higher prevalence of theC2 IGFBP3+ and C3 HHATL+ subtypes, with IGFBP3 being linked to apoptosis resistance and HHATL-mediated hedgehog signaling, which might increase stemness." (PMID 41383633, 2025).
HHATL also shares sentences with these, for which no sentence is quoted: tumor (2 papers); melanoma (1); nemaline myopathy 8 (1); skin squamous cell carcinoma (1).